RYR2 (ryanodine receptor 2)
Description:
Cytosolic calcium-activated calcium channel that mediates the release of Ca(2+) from the sarcoplasmic reticulum into the cytosol and thereby plays a key role in triggering cardiac muscle contraction. Aberrant channel activation can lead to cardiac arrhythmia. In cardiac myocytes, calcium release is triggered by increased Ca(2+) cytosolic levels due to activation of the L-type calcium channel CACNA1C. The calcium channel activity is modulated by formation of heterotetramers with RYR3. Required for cellular calcium ion homeostasis. Required for embryonic heart development.
Synonyms: RYR-2; ARVC2; VTSIP; ARVD2; RyR; VACRDS
Tractability: Small molecule: a structure with a bound ligand is known; a high-quality ligand is known; it belongs to a druggable protein family. Antibody: UniProt predicts a signal peptide or a membrane-spanning region; its Gene Ontology location is reachable by antibodies, with medium confidence. PROTAC: ubiquitination databases record sites on it; its protein half-life has been measured; a small molecule that binds it is known.
Target class: Ligand-gated ion channel; Ion channel; Ryanodine receptor
Safety:
Unwanted effects reported when the protein is acted on. In parentheses: how it was acted on, where the effect was seen, and who reports it.
cerivastatin-associated rhabdomyolysis (source: ClinPGx)
likelihood (source: ClinPGx)
statin-associated myopathy and myalgia (source: ClinPGx)
statin-associated myopathy or myalgia (source: ClinPGx)
Gene: Protein-coding gene on chromosome 1 (237,042,184 to 237,833,988, forward strand). Ensembl gene ENSG00000198626.
Subcellular location: Sarcoplasmic reticulum membrane
Subcellular location (Human Protein Atlas): Plasma membrane; Cytosol; Nucleoplasm
Pathways (Reactome):
Muscle contraction: Ion homeostasis
Transport of small molecules: Stimuli-sensing channels
Gene Ontology:
Molecular function: calcium-induced calcium release activity; calmodulin binding; enzyme binding; identical protein binding; intracellularly gated calcium channel activity; protein binding; protein kinase A catalytic subunit binding; protein kinase A regulatory subunit binding; ryanodine-sensitive calcium-release channel activity; suramin binding; calcium channel activity; transmembrane transporter binding; calcium ion binding; monoatomic ion channel activity; protein kinase binding; scaffold protein binding
Biological process: calcium ion transport; calcium ion transport into cytosol; calcium-mediated signaling; cardiac muscle contraction; cellular response to caffeine; detection of calcium ion; positive regulation of the force of heart contraction; regulation of atrial cardiac muscle cell action potential; regulation of AV node cell action potential; regulation of cardiac muscle contraction; regulation of cardiac muscle contraction by calcium ion signaling; regulation of cardiac muscle contraction by regulation of the release of sequestered calcium ion; regulation of heart rate; regulation of SA node cell action potential; regulation of ventricular cardiac muscle cell action potential; release of sequestered calcium ion into cytosol; release of sequestered calcium ion into cytosol by sarcoplasmic reticulum; response to caffeine; response to muscle activity; response to muscle stretch; response to redox state; type B pancreatic cell apoptotic process; cardiac muscle hypertrophy; cell communication by electrical coupling involved in cardiac conduction; cellular response to epinephrine stimulus; and 21 more
Cellular component: calcium channel complex; membrane; protein-containing complex; ryanodine receptor complex; sarcoplasmic reticulum; Z disc; junctional sarcoplasmic reticulum membrane; plasma membrane; sarcolemma; sarcoplasmic reticulum membrane; smooth endoplasmic reticulum; A band; extrinsic component of cytoplasmic side of plasma membrane; nuclear envelope; sarcomere
Genetic constraint (gnomAD): Loss-of-function variants: 138 observed, 374.57 expected, observed/expected ratio (o/e) 0.37, 90% interval 0.32 to 0.42. The upper end of that interval is the gene's LOEUF score, 0.42, which puts it in group 1 of 6, group 1 being the genes least tolerant of losing a copy. Missense variants: 3,596 observed, 4,820.1 expected, observed/expected ratio (o/e) 0.75, 90% interval 0.73 to 0.77. Synonymous variants: 1,773 observed, 1,759.8 expected, observed/expected ratio (o/e) 1.01, 90% interval 0.97 to 1.05.
Gene-disease validity (ClinGen):
ClinGen rates the evidence that RYR2 causes each of these diseases.
catecholaminergic polymorphic ventricular tachycardia (autosomal dominant): Definitive. Catecholaminergic polymorphic ventricular tachycardia (CPVT) is a severe genetic arrhythmogenic disorder characterized by adrenergically induced ventricular tachycardia (VT) manifesting as syncope and sudden death.
dilated cardiomyopathy (autosomal dominant): Limited. Cardiomyopathy which is characterized by dilation and contractile dysfunction of the left and right ventricles.
hypertrophic cardiomyopathy (autosomal dominant): Limited. A condition in which the myocardium is hypertrophied without an obvious cause.
arrhythmogenic right ventricular cardiomyopathy (autosomal dominant): Refuted.
Homologues: Orthologues: macaque RYR2 (99% identical), rabbit RYR2 (98% identical), dog RYR2 (98% identical), chimpanzee RYR2 (98% identical), mouse Ryr2 (97% identical), rat Ryr2 (97% identical), guinea pig RYR2 (96% identical), pig RYR2 (96% identical), zebrafish ryr2b (63% identical), Drosophila melanogaster RyR (48% identical), Caenorhabditis elegans unc-68 (43% identical). Paralogues in human: RYR3 (68% identical), RYR1 (66% identical), ITPR2 (14% identical), ITPR1 (13% identical), ITPR3 (13% identical).
Diseases named in the same sentence as RYR2 in open-access papers:
RYR2 is named in the same sentence as 246 diseases in open-access papers, as found by Europe PMC text mining. Sharing a sentence is not in itself a finding about the gene and the disease. The quoted sentences say what the papers report.
catecholaminergic polymorphic ventricular tachycardia (216 papers, 2008 to 2026). "GOF alterations in the RYR2 gene are known as a cause for catecholaminergic polymorphic ventricular tachycardia (CPVT) and cause increased spontaneous calcium release, contributing to ventricular arrhythmias and SCD." (PMID 41510139, 2026). "Some people who have a genetic predisposition to catecholaminergic polymorphic ventricular tachycardia (CPVT) have mutations in the RYR2 gene that lead to leaky RyR2 channels." (PMID 40422193, 2025). "A particularly intriguing association has emerged with RYR2 mutations, which are classically related to catecholaminergic polymorphic ventricular tachycardia (CPVT) and arrhythmogenic right ventricular cardiomyopathy (ARVC)." (PMID 41464675, 2025). "Catecholaminergic polymorphic ventricular tachycardia (CPVT) carries increased risk of ventricular arrhythmias due to altered Ca2+ regulation associated with mutations in the ryanodine receptor (RyR2)." (PMID 40612651, 2025). "Autosomal dominant mutations in the ryanodine receptor type 2 (RYR2) gene are often linked to cases of catecholaminergic polymorphic ventricular tachycardia." (PMID 38974714, 2024). "RYR2 mutations are responsible for catecholaminergic polymorphic ventricular tachycardia and exon 3 deletion syndrome." (PMID 39408732, 2024). "RYR2 gene (on 1q42.1-43) encodes the cardiac Ca2+ channel, and mutations have been linked to catecholaminergic polymorphic ventricular tachycardia (CPVT) and SCD." (PMID 38034995, 2023). "Multiple congenital RyR2 mutations cause calcium leakage from ER and lead to catecholaminergic polymorphic ventricular tachycardia (CPVT) in humans." (PMID 36453019, 2023). "Catecholaminergic polymorphic ventricular tachycardia (CPVT) is a stress-induced arrhythmic syndrome due to mutations in the Ca2+ release channel complex of ryanodine receptor 2 (RyR2)." (PMID 36672139, 2023). "Dominant gain of function RYR2 variants occur in 60–70% of patients with the autosomal dominant pro-arrhythmic condition catecholaminergic polymorphic ventricular tachycardia (CPVT)." (PMID 37122207, 2023). "Over 150 point mutations in the human type-2 ryanodine receptor gene (RYR2) have been identified to associate with catecholaminergic polymorphic ventricular tachycardia (CPVT1)." (PMID 37894987, 2023). "Abnormal Ca2+ leak from sarcoplasmic reticulum due to RyR2 dysfunction generates delayed afterdepolarization and can cause catecholaminergic polymorphic ventricular tachycardia in structurally normal hearts." (PMID 36975861, 2023). "A large number of naturally occurring RyR2 mutations have been associated with catecholaminergic polymorphic ventricular tachycardia (CPVT), a malignant arrhythmia that can cause syncope or sudden death." (PMID 35233070, 2022). "A gain-of-function missense mutation in the RYR2 (ryanodine receptor 2) gene can promote uncontrolled calcium leakage from the sarcoplasmic reticulum and cause catecholaminergic polymorphic ventricular tachycardia (CPVT)." (PMID 35461308, 2022). "RYR2 variants were well-reported to be associated with catecholaminergic polymorphic ventricular tachycardia (CPVT), but rarely reported in epilepsy cases." (PMID 36340715, 2022). "Most disease‐causing variants in RYR2 are missense variants and result in an autosomal dominant form of catecholaminergic polymorphic ventricular tachycardia (CPVT1, MIM 604772)." (PMID 35439358, 2022). "It has been well studied that RYR2 gene is discovered as a candidate pathogenic gene in catecholaminergic polymorphic ventricular tachycardia (CPVT, OMIM: 604772)." (PMID 36340715, 2022). "Activation of CaMKII-mediated phosphorylation of RYR2 at S2814 can activate the latent arrhythmic potential of catecholaminergic polymorphic ventricular tachycardia (CPVT) caused by RYR2 mutations." (PMID 36531185, 2022). "Heterozygous variants within the RYR2 gene cause the inherited arrhythmia syndrome catecholaminergic polymorphic ventricular tachycardia (CPVT)." (PMID 35439358, 2022).
catecholaminergic polymorphic ventricular tachycardia (continued). "Previous studies have identified the RYR2 mutations in the etiology of arrhythmogenic right ventricular dysplasia 2 and catecholaminergic polymorphic ventricular tachycardia." (PMID 33897349, 2021). "Sequence variants in RyR2, abundant in cardiac myocytes, are mostly linked to catecholaminergic polymorphic ventricular tachycardia (CPVT), a type of stress-induced cardiac arrhythmia." (PMID 33547325, 2021). "Genetic testing in the mother (III:5) revealed variants in the RYR2 gene related to cardiomyopathy, autosomal catecholaminergic polymorphic ventricular tachycardia, arrhythmogenic dysplasia of the right ventricle." (PMID 33829027, 2021). "Cardiac ryanodine receptor (RyR2) mutations are implicated in the potentially fatal catecholaminergic polymorphic ventricular tachycardia (CPVT) and in atrial fibrillation." (PMID 34440870, 2021). "Pathogenic variants in RYR2 are known to cause catecholaminergic polymorphic ventricular tachycardia." (PMID 34816733, 2021). "Both RYR2 R420W and S2246L are linked to catecholaminergic polymorphic ventricular tachycardia (CPVT); CALM1 N98S is linked to long QT syndrome, CPVT, idiopathic ventricular fibrillation, and sudden unexplained death." (PMID 34930847, 2021). "Mutations of RYR2 are characteristic for patients with catecholaminergic polymorphic ventricular tachycardia – up to 60 percent of cases are related to this gene mutation." (PMID 34393635, 2021). "Mutations in RyR2 linked to cardiac arrhythmia, including catecholaminergic polymorphic ventricular tachycardia (CPVT), have been identified as gain of function mutations such as N4104K, R4497C, and N4895D." (PMID 33474637, 2021). "Catecholaminergic polymorphic ventricular tachycardia (CPVT) is an inherited arrhythmia syndrome caused by autosomal dominant mutations most commonly in the cardiac ryanodine receptor (RYR2)." (PMID 33292493, 2020). "Variants in RYR2 are known to be a common cause of catecholaminergic polymorphic ventricular tachycardia (CPVT), a primarily electrical cardiac defect." (PMID 32466575, 2020). "Mutations in RyR2 are linked to catecholaminergic polymorphic ventricular tachycardia (CPVT) and arrhythmogenic right ventricular dysplasia type 2 (ARVD2)." (PMID 33104696, 2020). "The RyR2-P2328S mutation produces catecholaminergic polymorphic ventricular tachycardia (CPVT) and AF in hearts from homozygous RyR2P2328S/P2328S (denoted RyR2S/S) mice." (PMID 31028179, 2019). "Variants in RyR2 are classically linked to the inherited arrhythmogenic disease Catecholaminergic polymorphic ventricular tachycardia (CPVT), although RyR2 missense mutations have also been found in ACM patients." (PMID 31920701, 2019). "This conclusion is in agreement with clinical facts showing that patients with catecholaminergic polymorphic ventricular tachycardia (CPVT) due to RyR2 mutation only suffer arrhythmias after β-ARS." (PMID 32038301, 2019). "In vivo gene delivery of this recombinant CaM into the heart partially restored RyR2 refractoriness and decrease a chance of arrhythmias in the catecholaminergic polymorphic ventricular tachycardia (CPVT) model caused by calsequestrin mutation." (PMID 30574097, 2018). "RyR2 mutations leading to catecholaminergic polymorphic ventricular tachycardia have been associated with familial AF and genetic mouse models with these mutations show pronounced atrial Ca2+-handling abnormalities." (PMID 30166973, 2018). "Patients with catecholaminergic polymorphic ventricular tachycardia due to RyR2 mutations were shown to have impaired insulin secretion and glucose tolerance, and a similar phenotype was observed in knockin mice harboring these human RyR2 mutations." (PMID 28951826, 2017). "Catecholaminergic polymorphic ventricular tachycardia (CPVT) is one of the most lethal inherited cardiac arrhythmias mostly linked to cardiac ryanodine receptor (RyR2) mutations with high disease penetrance." (PMID 28961276, 2017).
catecholaminergic polymorphic ventricular tachycardia (continued). "For instance, gain-of-function mutations in RyR2 have been shown to predispose to catecholaminergic polymorphic ventricular tachycardia and AF by enhanced propensity for spontaneous Ca(2+) release." (PMID 27870913, 2016). "Catecholaminergic polymorphic ventricular tachycardia is a malignant inherited arrhythmia caused by mutations in the RyR2 and CASQ2 genes." (PMID 26153920, 2015). "These abnormalities are linked to mutations in the RyR2, located on chromosome 1q42.1–q4310, which lead to familial polymorphic ventricular tachycardia, CPVT, and arrhythmogenic right ventricular dysplasia type 2, ARVD/C." (PMID 25901278, 2015). "To date, more than 150 mutations in RyR2 have been associated with different forms of cardiac arrhythmias, including catecholaminergic polymorphic ventricular tachycardia (CPVT), catecholaminergic idiopathic ventricular fibrillation, and atrial fibrillation." (PMID 24743769, 2014). "Three children had deceased, two during an acute metabolic decompensation at the age of 33 days and 6 weeks, and the third, a 8-year-old girl with sudden cardiac death due to catecholaminergic polymorphic ventricular tachycardia (mutations in RyR2 gene)." (PMID 22642865, 2012). "The sudden cardiac death of a 9 year old girl was shown to be caused by catecholaminergic polymorphic ventricular tachycardia with mutations in the RyR2 gene." (PMID 22642865, 2012). "Catecholaminergic polymorphic ventricular tachycardia (CPVT) is a malignant inherited ion channel disorder predominantly caused by mutations in the cardiac ryanodine receptor (RyR2)." (PMID 22962621, 2012). "Catecholaminergic polymorphic ventricular tachycardia is a familial cardiac arrhythmia that is related to RYR2 or CASQ2 gene mutation." (PMID 22557844, 2012). "These distinctions extend to their associated disorders, with RYR2 mutations linked to cardiac arrhythmias such as catecholaminergic polymorphic ventricular tachycardia, while RYR1 mutations are typically associated with malignant hyperthermia and muscular pathologies." (PMID 40060969, 2025). "Genetic gain of RyR2 or loss of calsequestrin function is associated with the pro-arrhythmic condition catecholaminergic polymorphic ventricular tachycardia (CPVT) experimentally recapitulated in murine hearts carrying genetically altered RyR2 or calsequestrin-2." (PMID 37122224, 2023). "In addition, RyR2 hyperphosphorylation by PKA or by CaMKII are the major causes of Ca2+-dependent arrhythmia such as catecholaminergic polymorphic ventricular tachycardia (CPVT) and VTs associated with HF." (PMID 37122206, 2023). "Molecular autopsies mainly include the screening of the genes known to be involved in cardiac arrhythmias, such as KCNQ1, KCNH2, and SCN5A, which are associated with long QT syndrome, and RYR2, which is associated with major catecholaminergic polymorphic ventricular tachycardia (CPVT)." (PMID 37372445, 2023). "According to our previous study, RYR2 mutation is common in cardiac diseases, such as catecholaminergic polymorphic ventricular tachycardia, atrial fibrillation and ARVC/D, which may cause life-threatening ventricular arrhythmias and unexplained sudden death." (PMID 35526016, 2022). "However, mutations in the RYR2 gene have been associated with both catecholaminergic polymorphic ventricular tachycardias, in addition to AC." (PMID 35087879, 2021). "RYR2 has also been associated with catecholaminergic polymorphic ventricular tachycardias (CPVTs)." (PMID 35087879, 2021). "RyR2 mutations can result in severe disease phenotypes, and more than 150 mutations caused catecholaminergic polymorphic ventricular tachycardia (CPVT), and a few have been linked to arrhythmogenic right ventricular cardiomyopathy type 2 and idiopathic ventricular fibrillation." (PMID 33664309, 2021).